TRAPPC4 (trafficking protein particle complex subunit 4)
Description:
Core component of the TRAPP complexes which has a function of guanine nucleotide exchange factor activity for Rab1 GTPase (Probable). Plays a role in vesicular transport from endoplasmic reticulum to Golgi and autophagy. May play a role in dendrite postsynaptic membrane trafficking (By similarity).
Synonyms: SBDN; CGI-104; HSPC172; PTD009; TRS23; NEDESBA; SYNBINDIN
Tractability: Small molecule: it has a high-quality binding pocket. Antibody: UniProt places it where antibodies can reach, with medium confidence; its Gene Ontology location is reachable by antibodies, with medium confidence. PROTAC: ubiquitination databases record sites on it; its protein half-life has been measured.
Gene: Protein-coding gene on chromosome 11 (119,018,733 to 119,025,454, forward strand). Ensembl gene ENSG00000196655.
Subcellular location: Postsynaptic cell membrane; Golgi apparatus membrane; Endoplasmic reticulum; Vesicle
Subcellular location (Human Protein Atlas): Cytosol
Pathways (Reactome):
Vesicle-mediated transport: COPII-mediated vesicle transport; RAB GEFs exchange GTP for GDP on RABs
Extracellular matrix organization: Syndecan interactions
Gene Ontology:
Molecular function: protein binding
Biological process: autophagy; endoplasmic reticulum to Golgi vesicle-mediated transport; COPII vesicle coating; dendrite development; vesicle coating; vesicle-mediated transport
Cellular component: TRAPP complex; cytoplasm; cytosol; dendrite; endoplasmic reticulum; Golgi membrane; Golgi stack; postsynaptic membrane; synapse; synaptic vesicle; TRAPPII protein complex; TRAPPIII protein complex; vesicle; postsynaptic density membrane; presynaptic active zone
Genetic constraint (gnomAD): Loss-of-function variants: 27 observed, 21.9 expected, observed/expected ratio (o/e) 1.23, 90% interval 0.91 to 1.69. The upper end of that interval is the gene's LOEUF score, 1.69, which puts it in group 6 of 6, group 1 being the genes least tolerant of losing a copy. Missense variants: 243 observed, 281.06 expected, observed/expected ratio (o/e) 0.86, 90% interval 0.78 to 0.96. Synonymous variants: 126 observed, 108.05 expected, observed/expected ratio (o/e) 1.17, 90% interval 1.01 to 1.35.
Gene-disease validity (ClinGen):
ClinGen rates the evidence that TRAPPC4 causes each of these diseases.
neurodevelopmental disorder with epilepsy, spasticity, and brain atrophy (autosomal recessive): Definitive.
Homologues: Orthologues: macaque TRAPPC4 (99% identical), dog TRAPPC4 (99% identical), guinea pig TRAPPC4 (98% identical), mouse Trappc4 (98% identical), pig TRAPPC4 (98% identical), rat Trappc4 (98% identical), chimpanzee TRAPPC4 (91% identical), zebrafish trappc4 (87% identical), tropical clawed frog trappc4 (79% identical), Drosophila melanogaster Trs23 (58% identical), Caenorhabditis elegans trpp-4 (47% identical). Paralogues in human: TRAPPC1 (18% identical).
Diseases named in the same sentence as TRAPPC4 in open-access papers:
TRAPPC4 is named in the same sentence as 24 diseases in open-access papers, as found by Europe PMC text mining. Sharing a sentence is not in itself a finding about the gene and the disease. The quoted sentences say what the papers report.
colorectal cancer (5 papers, 2011 to 2021). A primary or metastatic malignant neoplasm that affects the colon or rectum. "To further validate the regulatory role of TRAPPC4 in the expression of PD-L1, we disrupted the expression of TRAPPC4 using two specific siRNAs in different colorectal cancer cell lines, including RKO and HCT-116 cells." (PMID 34518538, 2021). "Further IHC evaluation of paraffin-embedded human colorectal cancer tissues also showed a strong correlation between the levels of TRAPPC4 and PD-L1 proteins, with r = 0.8314 by Spearman’s coefficient analysis." (PMID 34518538, 2021). "In colorectal cancer cells, the trafficking protein particle complex 4 (TRAPPC4) modulates the location of p-ERK to activate the relevant signaling pathway." (PMID 22463874, 2012). "As little was known about the expression and localization of TRAPPC4 in colorectal cancer in vivo, we then compared its expression in normal colonic epithelium, adenoma and adenocarcinoma tissues by immunohistochemistry as described in Materials and methods." (PMID 21826244, 2011). "Another protein, TRAPPC4 may play a role in nucleocytoplasmic transport in colorectal cancer as enforced expression of TRAPPC4 correspondingly enhanced activation ERK1/2 and its consequent movement into the nucleus." (PMID 22672528, 2012). "Therefore, TRAPPC4 may play a role in nucleocytoplasmic transport in colorectal cancer, but this mechanism will require additional study." (PMID 21826244, 2011). "To dissect the role of TRAPPC4 in immune checkpoint regulation in vivo, we established stable syngeneic MC38 colorectal cancer cells by transducing lentiviruses expressing short-hairpin RNA (shRNA) to silence Trappc4." (PMID 34518538, 2021). "Further investigation found that when TRAPPC4 was depleted, activated ERK1/2 specifically decreased in the nucleus, which was accompanied with cell growth suppression and apoptosis in colorectal cancer (CRC) cells." (PMID 21826244, 2011).
colon cancer (2 papers, 2011 to 2021). "In the present study, murine tumor models show a remarkable CD8+ T-cell infiltration in colon tumor areas of intestinal epithelial cell-specific Trappc4-deficient (Trappc4△IEC) mice after azoxymethane (AOM)/dextran sodium sulfate (DSS) challenge." (PMID 34518538, 2021). "To investigate whether TRAPPC4 participates in regulating tumor immunity, we first examined the tumor-infiltrating lymphocytes (TILs) and PD-L1 expression in colon tumors with Trappc4 deficiency." (PMID 34518538, 2021). "We generated IEC-specific Trappc4-deficient (Trappc4△IEC, heterozygous) mice and exposed them to AOM/ DSS challenge to induce colon tumor formation." (PMID 34518538, 2021). "The proteomic analysis of colon cancer indicated that the protein levels of TRAPPC3, TRAPPC4, TRAPPC5, and TRAPPC8 significantly correlated with that of PD-L116." (PMID 34518538, 2021). "We found that, as a whole, overexpression of TRAPPC4 activated ERK1/2, while its depletion decreased pERK1/2 levels in the colon cancer-derived cell line SW1116." (PMID 21826244, 2011).
adenoma (1 paper, 2011). A neoplasm arising from the epithelium. "Here, we analyzed TRAPPC4 expression in human normal colonic epithelium, adenoma, and adenocarcinoma tissues by immunohistochemistry." (PMID 21826244, 2011). "TRAPPC4 was expressed more highly in the nucleus of CRC cells than in normal colonic epithelium or adenoma which corresponded with nuclear staining of pERK1/2." (PMID 21826244, 2011). "The results revealed that nuclear TRAPPC4 appears after normal epithelium tissue progresses to adenoma and adenocarcinoma." (PMID 21826244, 2011). "Moreover, we analyzed the association between TRAPPC4 and pERK1/2 or ERK1/2 staining in normal colonic epithelium, adenoma and adenocarcinoma." (PMID 21826244, 2011).
Cerebral atrophy (1 paper, 2023). Atrophy (wasting, decrease in size of cells or tissue) affecting the cerebrum. "Variants in multiple genes regulating endosomal trafficking and/or fusion of secretory vesicles [such as SMPD4, WDFY3, TRAPPC4, RAB18, VPS13B, EXOC7, EXOC8, VPS11], have been associated with the occurrence of microcephaly, cerebral atrophy, and neurodevelopmental delay." (PMID 36538041, 2023).
gastric cancer (1 paper, 2023). A primary or metastatic malignant neoplasm involving the stomach. "Indeed, it has been reported that TRAPPC4 can promote colorectal carcinogenesis by activating Wnt signaling or sustaining gastric cancer survival through extracellular signal-regulated protein kinase (ERK) signaling." (PMID 37603071, 2023).
intestinal cancer (1 paper, 2021). "Considering the key role of TRAPPC4 in subcellular membrane trafficking and intestinal cancer progression, we hypothesized that TRAPPC4 participates in regulating PD-L1 cellular trafficking and hence might mediate immune surveillance." (PMID 34518538, 2021).
Obesity (1 paper, 2024). Accumulation of substantial excess body fat. "However, patients bearing mutations of Trappc2, Trappc2l, Trappc4, Trappc6A/B, or Trappc10 do not develop obesity as patients with Trappc9 mutations do." (PMID 38889014, 2024).
cancer (6 papers, 2016 to 2025). A tumor composed of atypical neoplastic, often pleomorphic cells that invade other tissues. "Multiple reports have revealed that TRAPPC4 interacts with vital proteins in cancer-causing pathways and contributes to the molecular changes seen in cancer cells." (PMID 39769094, 2024). "For example, to date four TRAPP subunits are implicated in cancer: TrappC1 (Bet5), TrappC4 (Trs23), TrappC9, and TrappC10." (PMID 27066478, 2016). "Beyond the role of TRAPPC4 deficiency in neurodevelopmental disorders, fundamental research in the cancer field has uncovered links between TRAPPC4 dysregulation and carcinogenesis." (PMID 39769094, 2024). "Examples of newly added disease connections for TRAPP subunits include miscarriage for TrappC2, cancer for TrappC4, and TrappC9, intellectual disability and schizophrenia for TrappC9, and Alzheimer's disease for TrappC6." (PMID 27066478, 2016). "TRAPPC9, like TRAPPC4, has been shown to be upregulated in multiple cancer types." (PMID 39769094, 2024). "The strategic inhibition of multiple factors—DRG2, TRAPPC4, HIP1R, and CMTM6—represents a compelling approach to regulate PD-L1 surface levels on cancer cells, potentially reversing immune resistance mechanisms and amplifying the effectiveness of PD-1/PD-L1 blockade strategies." (PMID 40507229, 2025).
tumor (3 papers, 2021 to 2025). "Using in vivo and in vitro loss-of-function assays, we identified TRAPPC4 as a major player in regulating tumor immunity." (PMID 34518538, 2021). "Our previous studies showed that the expression of TRAPPC4 is associated positively with the clinical features of gastrointestinal malignancies including tumor volume, lymph node invasion, distant metastasis, tumor-node-metastasis staging, and overall survival of patients." (PMID 34518538, 2021). "The specific depletion of TRAPPC4 in tumor cells enhanced T-cell-mediated cytotoxicity toward tumor cells in vitro and augmented antitumor immunity in vivo." (PMID 34518538, 2021). "As shown by flow cytometry, PD-1 binding to tumor cells was dramatically impaired upon silencing of TRAPPC4." (PMID 34518538, 2021). "In line with the observation in the Trappc4△IEC CAC mouse model, silencing of Trappc4 in MC38 tumor cells eliminated subcutaneous tumor growth significantly." (PMID 34518538, 2021). "This interesting observation demonstrated that Trappc4 sensitized MC38 tumor cells to respond to anti-PD-L1 therapy." (PMID 34518538, 2021). "Consistently, while silencing of TRAPPC4 induced slight apoptosis of tumor cells, TRAPPC4-silenced tumor cells were more vulnerable to T-cell cytotoxicity as a result of reduced PD-1/PD-L1 binding." (PMID 34518538, 2021). "Overexpression of Trappc4 sensitizes tumor cells to checkpoint therapy in murine tumor models, suggesting TRAPPC4 as a therapeutic target to enhance anti-tumor immunity." (PMID 34518538, 2021). "In mouse-bearing sh-Trappc4-expressing MC38 tumors, we observed an increased infiltration of activated CD8+ T cells as well as an enhanced antitumor immune microenvironment., suggesting a regulatory role of TRAPPC4 in tumor immunity." (PMID 34518538, 2021). "To further delineate the alteration of the TME upon silencing of Trappc4 in tumor cells, we analyzed the TILs in mouse-bearing Trappc4-silenced tumors using flow cytometry assays." (PMID 34518538, 2021). "Silencing of TRAPPC4 led to the sequential degradation of PD-L1 in lysosomes, thus reducing the overall PD-L1 reserve in tumor cells, as well as that on the cell surface." (PMID 34518538, 2021). "Targeting TRAPPC4 may attenuate PD-L1 recycling and synergize with immune checkpoint blockade to enhance anti-tumor immunity." (PMID 40507229, 2025). "The intricate regulatory roles of DRG2, TRAPPC4, HIP1R, and CMTM6 in PD-L1 trafficking and stability present compelling opportunities for therapeutic intervention to enhance anti-tumor immunity." (PMID 40507229, 2025). "TRAPPC4, HIP1R, and PTMs orchestrate the dynamic regulation of PD-L1, enabling tumor cells to fine-tune their expression and sustain immune suppression." (PMID 40507229, 2025). "Remarkably, Trappc4-OE MC38 tumors exhibited a better response to the anti-PD-L1 mAb, with impaired tumor growth, smaller tumor volumes, and reduced tumor weights." (PMID 34518538, 2021). "Here the authors show that TRAPPC4, a core subunit of TRAPP complex, is required for RAB11-mediated recycling of PD-L1, affecting T-cell-mediated anti-tumor immune responses." (PMID 34518538, 2021). "In line with the increasing TILs in the tumor areas, significantly lower PD-L1 levels were observed in Trappc4△IEC mice, indicating that the PD-L1 protein level correlated with that of TRAPPC4." (PMID 34518538, 2021). "However, whether TRAPPC4 participates in modulating tumor immunity remains unclear." (PMID 34518538, 2021). "The T-cell-mediated killing assay showed that co-incubation with activated human peripheral blood mononuclear cells (PBMCs) led to significantly more tumor cell apoptosis in the absence of TRAPPC4." (PMID 34518538, 2021). "TRAPPC4 interacts with PD-L1 in recycling endosomes, acting as a scaffold between PD-L1 and RAB11, and promoting RAB11-mediated recycling of PD-L1, thus replenishing its distribution on the tumor cell surface." (PMID 34518538, 2021).
tumor (continued). "We also identify TRAPPC4 as a potential therapeutic target, which in combination with ICB, could eliminate immune evasion of tumor cells." (PMID 34518538, 2021). "Intriguingly, only knockdown of TRAPPC4, but not the other tested subunits, reduced the PD-1 binding on the tumor cell surface significantly." (PMID 34518538, 2021). "The upregulation of PD-L1 levels in TRAPPC4-OE tumor cells led to a suppressive TME with less infiltration of cytotoxic CD8+ T cells, which may be one of the predominant reasons accounting for the overgrowth of TRAPPC4-OE tumors." (PMID 34518538, 2021). "In this work, we find that TRAPPC4 maintains the expression of PD-L1 by acting as a scaffold for PD-L1 and RAB11 to coordinate RAB11-mediated recycling of PD-L1 and protecting PD-L1 from lysosomal degradation, ultimately promoting immune evasion and tumor progression." (PMID 34518538, 2021).
neurodevelopmental disorder (2 papers, 2024). A behavioral and cognitive disorder with onset during the developmental period that involves impaired or aberrant development of intellectual, motor, or social functions. "More recently, TRAPPC4 was linked to a rare neurodevelopmental disorder, where an autosomal recessive pathogenic variant was identified in three unrelated families via WES and cell-based functional analyses." (PMID 39769094, 2024). "Despite the recent evidence that TRAPPC4 deficiency is associated with a neurodevelopmental disorder, disease modelling advancements to further elucidate the neurological phenotype have not yet been attempted, with current functional testing being limited to patient fibroblasts and yeast models." (PMID 39769094, 2024).
colorectal (1 paper, 2011). "Thus, the alteration in localization of TRAPPC4 may be related to colorectal carcinogenesis." (PMID 21826244, 2011).
metabolic disorders (1 paper, 2023). "In addition to these genes, variants were found in seven genes (ALDOB, MASP1, KIAA1109, TRAPPC4, SMARCAL1, HERC1, RRAS2) that were previously not reported in MPS but associated with other metabolic disorders." (PMID 37091798, 2023).
TRAPPC4 also shares sentences with these, for which no sentence is quoted: adenocarcinoma (1 paper); amyotrophic lateral sclerosis (1); Brain atrophy (1); cervical cancer (1); epilepsy (1); infection (1); Intellectual disability (1); lysosomal storage disorder (1); microcephaly (1); neurodegenerative disease (1); Neurodevelopmental delay (1); Parkinson disease (1).